RNU6-104P (RNA, U6 small nuclear 104, pseudogene)
Gene: Small nuclear RNA gene on chromosome 8 (43,303,376 to 43,303,482, forward strand). Ensembl gene ENSG00000238509.
Homologues: Orthologues: chimpanzee U6 (99% identical), guinea pig U6 (79% identical), dog U6 (76% identical), pig U6 (69% identical). Paralogues in human: RNU6-819P (89% identical), RNU6-1021P (85% identical), RNU6-127P (84% identical), RNU6-286P (84% identical), RNU6-631P (84% identical), RNU6-749P (84% identical), U6 (84% identical), RNU6-1049P (83% identical), RNU6-1239P (83% identical), RNU6-1268P (83% identical), RNU6-473P (83% identical), RNU6-617P (83% identical), and 1286 more.